INS (insulin)
Diseases named in the same sentence as INS in open-access papers (continued):
Sharing a sentence is not in itself a finding about the gene and the disease.
diabetes (continued). "Clinical trials investigating the role of microbiota in pre-diabetes and obesity have shown that the effect of probiotics on metabolic variables such as weight, body mass index (BMI), glucose, postprandial insulin, and HbA1c can differ." (PMID 37038214, 2023). "Pancreatic β-cell apoptosis is the determining factor for the decline of β-cell function and impaired insulin secretion in diabetes." (PMID 37920252, 2023). "The prevalence of type 2 diabetes, a multifactorial disease characterized by progressive deterioration of insulin secretion and action, is on the rise and accounts for more than 90% of individuals diagnosed with diabetes." (PMID 37891946, 2023). "Our analysis also allowed us to provide evidence that would refine this theory on motivation as it applies to the use of mobile apps in the population with diabetes requiring insulin." (PMID 36826987, 2023). "Diabetes is a metabolic disease typified by chronic hyperglycemia resulting from inadequate insulin secretion or impaired insulin action owing to impaired pancreatic β‐cell function or insulin resistance respectively." (PMID 35841183, 2023). "Those with lower eGDR were typically older, had a longer diabetes duration, required higher insulin doses, and had an adverse vascular profile (p < 0.05)." (PMID 36495341, 2023). "Patients with advanced DKD had longer duration of diabetes, more micro and macrovascular complications, more patients requiring insulin therapy, lower haemoglobin and eGFR at presentation, more chronic histology and isolated C3 deposits on kidney biopsy." (PMID 37492933, 2023). "Diabetes is characterized by hyperglycemia, affecting carbohydrate, fat, and protein metabolism resulting from abnormal insulin secretion, insulin resistance, or both factors." (PMID 36677559, 2023). "Until then, a multiple daily insulin injection scheme is considered the first choice in youth with WS1 diabetes." (PMID 36835101, 2023). "The decrease in serum insulin levels in animal models after STZ induction is used as a sign of the inducement of diabetes." (PMID 35237941, 2023). "We included 18 ICU patients with type 2 diabetes receiving empagliflozin (10 mg daily) and insulin to target glucose range of 10–14 mmol/l according to our liberal glucose control protocol for patients with diabetes (treatment group)." (PMID 37194077, 2023). "In the current study, rats progressed from a healthy to prediabetic phenotype by 16 weeks of age and developed diabetes by 24 weeks, with severe impairments in insulin production." (PMID 37233701, 2023). "Integration of an insulin biosensor to work in parallel with glucose monitoring will undoubtedly facilitate safe and precise management of diabetes and improve the quality of life of those living with the condition." (PMID 37504117, 2023). "Animal models of diabetes can be induced by streptozotocin (STZ) injections which result in decreased circulating insulin and hypothermia." (PMID 37638180, 2023). "Diabetes mellitus (DM) is a medical condition described by inadequate secretion of insulin and/or diminished tissue responsiveness to insulin at any number of sites along the complex hormonal action pathways." (PMID 38111646, 2023). "These protocols are of great interest in the field of regenerative medicine for the treatment of diabetes, as they hold the potential to produce insulin-secreting cells that can replace damaged or dysfunctional pancreatic islets in diabetic patients." (PMID 37929027, 2023). "About 36.9% reported having a family history of diabetes, 60.8% reported taking medication as a treatment for diabetes, whereas 16.9% took both insulin and medication." (PMID 37237354, 2023). "There are several medications to treat diabetes mellitus, such as insulin and metformin, which are costly and responsible for different types of side effects in the human body." (PMID 38601799, 2023).
diabetes (continued). "Diabetic patients were identified based on fasting plasma glucose levels of at least 126 mg/dL, taking insulin or anti-diabetic medication, being diagnosed with DM by a physician, and having an HbA1c level of 6.5% as a cut-off point for uncontrolled diabetes." (PMID 37790059, 2023). "The reduction in insulin secretion occurs because people suffering from diabetes and obesity have fewer incretin hormones that increase insulin secretion." (PMID 37049602, 2023). "Diabetes mellitus is a multifaceted metabolic illness marked by persistent high blood sugar levels due to irregularities in the production or function of insulin." (PMID 38283440, 2023). "Insulin resistance is compensated by the hypersecretion of insulin in beta cells in the early stages of diabetes, and the clinical course of the disease occurs when pancreatic functional reserves eventually cannot cope with the required insulin secretion." (PMID 37298118, 2023). "Type-2 diabetes mellitus (T2DM) is a metabolic disorder marked by high fasting and post-prandial circulating blood glucose, increased insulin resistance, and a progressive loss of pancreatic β-cell insulin secretion." (PMID 36472154, 2023). "Consider the management of diabetes, pioneered by the discovery of insulin over a century ago, where it has since saved innumerable patients’ lives." (PMID 37036866, 2023). "The main objective of our study was to determine the effectiveness of insulin pump therapy in type 1 diabetic patients in terms of their satisfaction as assessed by the DTSQ (Diabetes Treatment Satisfaction Questionnaire)." (PMID 37185052, 2023). "These devices are especially important for people with diabetes treated with insulin therapy and have been extensively studied in outpatient settings." (PMID 37736430, 2023). "The Ingenuity Pathway Analysis (IPA) engine (version 70750971) was used for a central analysis and construction of the signaling pathway networks of insulin secretion and type 2 diabetes mellitus." (PMID 36992977, 2023). "No individuals were on immunosuppressive therapy at the time of sampling; individuals with diabetes were treated with insulin." (PMID 36600150, 2023). "Children with T1D are dependent on their parents and adults in their immediate surroundings to care for their diabetes and insulin dosing for meals." (PMID 38004219, 2023). "Sie sind mit einer Reihe von metabolischen Komplikationen wie Insulin-Resistenz, Diabetes mellitus, Hypertriglyzeridämie und Steatosis hepatis vergesellschaftet, häufig auch mit Akanthosis nigricans, polyzystischem Ovar-Syndrom und eruptiven Xanthomen." (PMID 37101022, 2023). "Another Asian study from the Joint Asia Diabetes Evaluation Registry demonstrated that 21% of T2DM patients received insulin therapy to control their diabetes." (PMID 37264625, 2023). "Other risk factors contributing to type 2 diabetes in children include a family history of diabetes, being born to a mother with diabetes during pregnancy (gestational diabetes), or other medical problems that affect insulin metabolism." (PMID 36832487, 2023). "The development of diabetes mellitus after menopause is thought to occur through alterations in insulin secretion, insulin sensitivity, and glucose effectiveness." (PMID 38089629, 2023). "The major classes of pharmacological agents for diabetes are largely divided into three types: insulin secretagogues, insulin sensitizers, and carbohydrate digesting enzyme inhibitors." (PMID 36771665, 2023). "Istek and Karakurt reported that individuals with diabetes should schedule routine checkups, monitor their blood sugar levels, follow insulin and medication regimens, and plan their diet and exercise regimens to achieve glycemic control." (PMID 38074026, 2023). "When compared to the control group, blood glucose and insulin levels in the diabetes group were significantly higher and lower, respectively (both, P < 0.001)." (PMID 37081849, 2023).
diabetes (continued). "Presently, the therapeutic options for diabetes encompass insulin as well as a range of oral antidiabetic medications, including sulfonylureas, biguanides, and glinides." (PMID 37954853, 2023). "Approximately 5% of patients with diabetes suffer from Type 1 Diabetes (T1D), an autoimmune condition in which patients rely on exogenous insulin." (PMID 36984824, 2023). "These compounds have been found to improve insulin sensitivity and lower blood sugar levels in animal models of diabetes." (PMID 37048331, 2023). "Patients with LADA showed lower fasting glucose values, fewer diabetic complications, younger age at diagnosis of diabetes, higher insulin use, and higher eGDR in comparison to patients with T2D." (PMID 37120620, 2023). "Diabetes mellitus (DM), a metabolic disorder, is defined as the body’s inability to produce or effectively retaliate to insulin." (PMID 36836916, 2023). "Of the more than 500 million people worldwide with diabetes, an estimated 71 million rely on insulin." (PMID 37971985, 2023). "We found that 56% of patients in the group with insulin treatment were with uncontrolled diabetes on admission." (PMID 36983573, 2023). "The rapid shift of patients from OHA to subcutaneous insulin in a short span must be alarming to the physician managing diabetes and needs extensive workup to look upon the etiology of the same." (PMID 38249240, 2023). "Animal studies showed that apple peel supplementation leads to the improvement of the major disorders which are the foundation of diabetes, i.e., insulin and fasting glucose levels decrease." (PMID 36983908, 2023). "Diabetes mellitus (DM) is a collection of metabolic disorders characterized by insufficient insulin secretion, decreased insulin action, or a combination of both, leading to hyperglycemia." (PMID 37049340, 2023). "The diabetes provider made insulin dose changes based on the data provided by the participant during follow-up calls." (PMID 37313442, 2023). "Diabetes mellitus (DM) is a metabolic disorder due to defective secretion of insulin or its impaired biological action in the human body, resulting in hyperglycemia or triggering kidney and nerve dysfunctions." (PMID 36850616, 2023). "Type 1 Diabetes Mellitus (T1DM) is a chronic disease characterized by the inability of the body to produce insulin due to the autoimmune destruction of the beta cells in the pancreas." (PMID 36983604, 2023). "The Hypoglycaemia – MEasurement, ThResholds and ImpaCtS (Hypo-METRICS) smartphone app was developed to investigate the impact of hypoglycemia on daily functioning in adults with type 1 diabetes mellitus or insulin-treated type 2 diabetes mellitus." (PMID 37773626, 2023). "Diabetes mellitus is a heterogeneous metabolic disorder that is characterized by the presence of hyperglycaemia due to the impairment of insulin secretion and/or defective insulin action leading to peripheral insulin resistance." (PMID 37373351, 2023). "Diabetes und/oder Insulin-Resistenz noch nicht in Studien als primärer Endpunkt nachgewiesen wurde, ist doch davon auszugehen, dass Patient:innen mit Diabetes ähnlich wie nicht-diabetische Kollektive davon profitieren." (PMID 37101043, 2023). "Diabetes mellitus is a worldwide rapidly disseminated metabolic disorder that is distinguished by persistent hyperglycemia because of the flaw in insulin action, insulin secretion, or both." (PMID 37197584, 2023). "Multivariate linear regression analysis was used to assess factors affecting HRQOL among diabetes patients treated with insulin." (PMID 37143082, 2023). "Diabetes mellitus is a collection of metabolic diseases characterised by chronic hyperglycaemia due to diminished insulin secretion and synthesis and/or increased insulin resistance." (PMID 37048081, 2023).
diabetes (continued). "Recent studies have demonstrated that fluoxetine effectively reduces depression severity in patients with diabetes with controlled blood glucose and improved insulin sensitivity in patients with obesity and diabetes mellitus." (PMID 37046230, 2023). "For the insulin hormone, MultiCens detected PRKCQ-AS1, a natural antisense lncRNA for the diabetes drug-target and insulin signaling regulator PRKCQ (Protein kinase C theta)." (PMID 37093889, 2023). "Pharmacological and non-pharmacological treatment strategies have the potential to improve insulin sensitivity and increase the chances of survival in patients with diabetes." (PMID 38027557, 2023). "Different types of insulin therapeutic regimens (ITRs) have also been associated with overweight/obesity, as observed in the Diabetes Control and Complications Trial (DCCT) where the use of intensive insulin therapy was closely associated with weight gain." (PMID 36823646, 2023). "Our findings also showed that insulin use, great number of diabetes’ complications, and early onset T2DM (before age 55) were all linked to higher risk of all-cause dementia." (PMID 36804018, 2023). "Current pharmacologic treatment options for children and adolescents with diabetes are limited to insulin, metformin, and two glucagon-like peptide-1 (GLP-1) receptor agonists, i.e., daily liraglutide and once-weekly exenatide extended release." (PMID 38089044, 2023). "A seven-stage protocol efficiently converts human ESCs into insulin-producing cells, offering a potential therapy for diabetes." (PMID 38203514, 2023). "Diabetes mellitus (DM) is characterized by poor glycemic control due to either inadequate insulin production by the pancreatic β-cells (type 1 diabetes; T1DM) or failure to compensate for insulin resistance (type 2 diabetes; T2DM)." (PMID 37243756, 2023). "This type of diabetes mellitus is characterized by decreased insulin secretion and normal insulin sensitivity." (PMID 37509329, 2023). "This extensive European study found a notable association: individuals who adhered closely to the MD experienced a reduced probability of insulin-independent diabetes." (PMID 38201865, 2023). "β‐cell–specific METTL14 knockout mice exhibited reduced β‐cell proliferation, insulin degranulation, and early‐onset diabetes, similar to those with human T2DM." (PMID 36891946, 2023). "Compared with patients with complete insulin-deficient T1DM, TP patients were older (62.59 ± 10.41 vs 44.01 ± 17.22 years, P < 0.001) with shorter diabetes duration (20 vs 132 months, P < 0.001) but similar BMI (20.33 ± 2.39 vs 20.92 ± 1.76 kg/m2, P = 0.079)." (PMID 36860372, 2023). "Declining insulin sensitivity and defects in insulin secretion are crucial markers of the evolution from prediabetes toward diabetes." (PMID 37202497, 2023). "This research filled some gaps in the literature because no systematic reviews are looking into the relationship between statin therapy and a decline in insulin sensitivity/insulin resistance, which frequently results in the onset of diabetes." (PMID 37465091, 2023). "Other types of diabetes mellitus include clinical entities that are developed due to genetic defects in insulin secretion or action, abnormalities that impede insulin secretion, mitochondrial impairments, and conditions that impair glucose tolerance." (PMID 36979649, 2023). "Rodents showing signs of pre-diabetes after a high-fat diet, after a monthly 40% caloric restriction, showed a decrease in body weight and regained insulin sensitivity." (PMID 36975496, 2023). "The inverted U pattern of IGF-I bioactivity is probably caused by direct modulating effects of insulin (and IGFBP-1) on IGF-I bioactivity during the natural course from fasting normoglycemia to frank diabetes." (PMID 36901984, 2023). "Diabetes mellitus (DM) is a chronic illness due to inadequate insulin production by pancreatic β cells." (PMID 38139804, 2023).
diabetes (continued). "Feelings of hopelessness related to chronic disease, impaired quality of life and accessibility to potential lethal drugs as insulin are only some factors that have an impact on the complex relationship between suicide and diabetes." (PMID 37492440, 2023). "Dyslipidemia is a common finding among these patients, even in the first years of life, whereas diabetes tends to develop during puberty, but subjects can express elevated fasting insulin levels and mild insulin resistance at a younger age." (PMID 37501786, 2023). "This form of diabetes is characterized by decreased insulin signaling in the CNS and cognitive deficit." (PMID 36834685, 2023). "A patient with early onset was also reported, diagnosed with diabetes at age eight and requiring insulin administration at presentation." (PMID 36671511, 2023). "Insulin has been widely used, and has been known for decades in patients hospitalized and suffering from diabetes." (PMID 36839456, 2023). "Type 1 diabetes mellitus (T1DM), which is a deficient production or dysfunction of insulin, has become a worldwide and provincial health concern with a significantly increasing incidence." (PMID 36808709, 2023). "Diabetes mellitus, particularly type 2 diabetes mellitus (T2DM), more common during the menopausal transition due to increased rates of resistance to insulin and upper body fatty tissue accumulation, is predisposed to as a result." (PMID 38288203, 2023). "Collectively, these studies underscore the complex and multifaceted roles that these enzymes play in insulin regulation, offering potential new avenues for understanding and treating metabolic disorders related to insulin resistance and diabetes." (PMID 38203517, 2023). "The remaining 10 criteria are novel and address the treatment of type 2 diabetes mellitus, including insulin (alone or in combination with liraglutide), glargine insulin, GLP-1, IDPP-4, and ISGLT-2 inhibitors." (PMID 37864147, 2023). "Diabetes mellitus (DM) is a chronic disease of the endocrine system characterized by hyperglycemia mainly induced by insufficient insulin secretion or insulin resistance." (PMID 38313844, 2023). "Diabetes mellitus (DM) is marked by high blood glucose resulting from the body’s insensitivity to the actions of insulin." (PMID 37187523, 2023). "Physicians should be aware of the risk of such discordance in patients with atrial fibrillation, advanced age, and insulin-treated diabetes mellitus." (PMID 36826530, 2023). "The literature indicates that along with good glycemic control and insulin replacement, the best way to reduce the chronic complications of diabetes is to educate the patient and their family." (PMID 37900142, 2023). "The CBGM system provides real-time glucose readings, allowing individuals to understand their glucose trends, make informed decisions regarding their diabetes management, and adjust their doses of insulin or other medications accordingly." (PMID 37568877, 2023). "A transdermal patch that delivers insulin at high glucose concentrations can offer tremendous advantages to ease the concern of safety and improve the quality of life for people with diabetes." (PMID 37718654, 2023). "Providers were invited to identify well-managed patients from their clinic who either lived with diabetes (type 1 or type 2 on insulin) or cared for a loved one with diabetes to serve as DSC." (PMID 37535407, 2023). "Diabetes mellitus (DM) is a metabolic disorder characterized by increased blood glucose levels resulting from either defective insulin secretion, insulin activity, or both." (PMID 36779109, 2023). "Its use should be also considered in people with a recent diagnosis of diabetes presenting prevalent hyperglycemia or in people with autoimmune diabetes in the stage of “honeymoon” with reduced insulin requirements." (PMID 37676398, 2023). "The most prevalent form of diabetes with insulin resistance and a relative insulin deficit is type 2." (PMID 37624794, 2023).